SOD1 (superoxide dismutase 1)
Diseases named in the same sentence as SOD1 in open-access papers (continued):
Sharing a sentence is not in itself a finding about the gene and the disease.
Parkinson disease (140 papers, 2008 to 2026). A progressive degenerative disorder of the central nervous system characterized by loss of dopamine producing neurons in the substantia nigra and the presence of Lewy bodies in the substantia nigra and locus coeruleus. "In the Parkinson disease SNc, the formation of wild-type disSOD1 pathology is associated with severe copper deficiency and concomitant SOD1 protein overexpression in this degenerating region." (PMID 40042537, 2025). "Structurally-disordered wild-type and mutant SOD1 are thought to contribute to neurodegeneration in Parkinson disease and ALS through simultaneous loss- and gain-of-protein functions." (PMID 40563111, 2025). "Specific restriction of tissue copper deficiency and SOD1 protein overexpression to the SNc in future studies would better reflect the distribution of these changes in the Parkinson disease brain." (PMID 40042537, 2025). "By contrast, we recently reported a wildtype Cu/Zn-superoxide dismutase (SOD1) proteinopathy associated with neuronal loss in the Parkinson’s disease SN closely resembling misfolded SOD1 linked to neuronal death in SOD1-associated ALS spinal cord." (PMID 35760970, 2022). "Our data collected from post-mortem Parkinson disease tissues suggest that copper deficiency and increased SOD1 protein levels trigger the development of disSOD1 pathology by altering physiological SOD1 PTMs and promoting the addition of atypical PTMs to the protein." (PMID 40042537, 2025). "Overall, we have identified a range of atypical PTMs likely to impact the structural and functional integrity of SOD1 within the degenerating SNc in post-mortem Parkinson disease brain, which have the capacity to underlie the selective accumulation of disSOD1 pathology in this region." (PMID 40042537, 2025). "We applied proteomic mass spectrometry and synchrotron-based biometal quantification to post-mortem brain tissues from the SNc of Parkinson disease patients and age-matched controls to uncover key factors underlying the formation of wild-type SOD1 pathology in this disorder." (PMID 40042537, 2025). "We propose that this underlies increased SOD1 oxidation and glycation in the Parkinson disease SNc in this study, both of which increase the propensity of the protein to aggregate and may contribute to the accumulation of disSOD1 pathology in this region." (PMID 40042537, 2025). "Having established that SOD1 protein overexpression and copper deficiency promote SOD1 PTM alterations in SOCK mice matching those observed in Parkinson disease patients, we next sought to confirm that these changes result in enzymatic dysfunction and aggregation of the protein." (PMID 40042537, 2025). "This is in line with the previous findings by our group demonstrating stoichiometric imbalance in Cu:Zn binding to SOD1 aggregates in the Parkinson disease SNc, reinforcing the role of copper deficiency in destabilizing protein structure and promoting the formation of unstable isoforms." (PMID 40042537, 2025). "Similar as mutant SOD1 (mSOD1), intraneuronal accumulation of misfolded Parkin and polyglutamine (polyQ)-expanded Huntingtin (Htt) proteins is associated with the neurodegenerative disorders Parkinson’s and Huntington’s disease, respectively." (PMID 24691167, 2014). "Overall, we provide clear empirical evidence that significant wild-type disSOD1 pathology accompanies altered SOD1 PTMs in an environment of copper deficiency and increased wild-type SOD1 protein overexpression, suggesting that these pathways may drive disSOD1 pathology in the Parkinson disease SNc." (PMID 40042537, 2025). "Given the importance of copper binding for SOD1 structure, we next measured the pI of enzymatically active SOD1 protein in the Parkinson disease SNc to evaluate the impact of decreased copper binding on SOD1 protein conformation." (PMID 40042537, 2025). "Mirroring changes observed in the Parkinson disease SNc, we identified significant increases in 10 atypical SOD1 PTMs in SOCK mice." (PMID 40042537, 2025).
Parkinson disease (continued). "Here, we quantified metals bound to SOD1 dimers isolated from post-mortem brain tissues of Parkinson disease patients and age-matched controls, in whom the absence of SOD1 gene mutations had been confirmed." (PMID 40042537, 2025). "We demonstrated that the biochemical profile introduced in SOCK mice promotes the same post-translational modifications and the development of Parkinson-like wild-type SOD1 pathology in the midbrain and cortex." (PMID 40042537, 2025). "This was achieved by replicating two key changes identified in the post-mortem Parkinson disease SN: elevated SOD1 protein levels and a decrease in neuronal copper levels." (PMID 40563111, 2025). "We chose to overexpress human SOD1, rather than mouse SOD1, in our model given our aim was to replicate SOD1 pathology observed in the Parkinson disease brain and mouse SOD1 aggregates differently to the human isoform." (PMID 40563111, 2025). "It is unlikely that increased deamidation in this brain region induces structural disorder in SOD1 protein given we previously identified minimal disSOD1 in the Parkinson disease OCx." (PMID 40042537, 2025). "Atypical wild-type superoxide dismutase 1 (SOD1) protein misfolding and deposition occurs specifically within the degenerating substantia nigra pars compacta (SNc) in Parkinson disease." (PMID 40042537, 2025). "Here, we characterize atypical molecular changes in SOD1 in the human Parkinson disease SNc and demonstrate that recapitulating these changes in mice promotes the development of Parkinson-like wild-type disSOD1." (PMID 40042537, 2025). "Aggregates are mostly extracellular but are also seen within the cells (eg, α-synuclein aggregates in motor neurons in Parkinson’s disease, SOD1 aggregates in ALS disease, and amylin aggregates in pancreatic beta-cells in type 2 diabetes)." (PMID 32378382, 2020). "We examined the neuropathological microfeatures Lewy bodies, aggregations of superoxide dismutase 1 (SOD1) and neuromelanin in human post-mortem Parkinson's disease tissue." (PMID 34123146, 2020). "Well characterized toxic oligomers are those of α-synuclein (Parkinson’s disease), SOD1 (ALS), and serum amyloid protein (SAP)." (PMID 32378382, 2020). "The misfolded SOD1 was also detected in CSF from a subset of Parkinson’s disease and progressive supranuclear palsy, albeit with smaller amounts than those in sALS." (PMID 31744522, 2019). "In some rare genetic forms of ALS and Parkinson’s disease, mutant SOD1 and mutant α-synuclein are suggested to lead to a ‘pure’ form of endoplasmic reticulum stress, due to their accumulation within the endoplasmic reticulum." (PMID 27190028, 2016). "We have developed and utilized the ZNStress assay with transgenic zebrafish carrying hsp70-DsRed in the context of wildtype sod1 to identify neurotoxic genes involved in Parkinson’s disease (unpublished data)." (PMID 27460825, 2016). "In our study, in PD patients with NFE2L2 variants (117E and 141H), we observed the effects of the NFE2L2 variants on its downstream gene expression including GSTM1 and SOD1, a major antioxidant enzyme in Parkinsonism." (PMID 26887053, 2016). "In neurodegenerative diseases such as Prion disease, Parkinson’s and Alzheimer’s, toxic factors such as prions, tau, amyloid β, α-synucleins, aggregates of superoxide dismutase 1 were shown to be present in EVs eliciting neurotoxicity." (PMID 26154133, 2015). "SNO-PDI accentuates the misfolding of synphilin in Parkinson disease and S-nitrosylation also increases mutant SOD1 aggregation via incorrect disulphide cross-linking of the immature, misfolded mutant SOD1, leading to neuronal cell death." (PMID 26052512, 2015). "Here, we show a client-specific role for COMMD1 on the aggregation of protein species associated with the neurodegenerative disorders SOD1-linked ALS, Parkinson’s disease and Huntington’s disease." (PMID 24691167, 2014).
Parkinson disease (continued). "Previously, mutations in SOD1, ANG, FUS/TLS, TARDBP and CHMP2B have been identified in patients with a range of clinical phenotypes, including combinations of FTD, Parkinson’s disease, and ALS." (PMID 23155438, 2012). "The pI values found for the oxidized SOD1 proteins are well consistent with those found for the oxidatively modified isoforms of SOD1 (pI 6.3, 6.0, 5.7, and 5.0) extracted from Alzheimer and Parkinson disease brains." (PMID 20808835, 2010). "SOD1 is mutated in 20% of the familial ALS patients and increased SOD1 activity is neuroprotective in a mouse model of chemically induced Parkinson’s disease." (PMID 22069568, 2010). "Collectively, these data suggest that decreased SOD1 copper binding may contribute to the accumulation of disSOD1 in the Parkinson disease SNc." (PMID 40042537, 2025). "Increases in atypical SOD1 PTMs that promote its aggregation may be compounded by dysregulation of SOD1 glycosylation in the Parkinson disease SNc, which likely signifies disruption of nascent, immature SOD1 trafficking." (PMID 40042537, 2025). "The remaining 16 physiological PTM changes were unique to SOCK mice and were all down-regulated compared with SOD1 isolated from the healthy aged human SNc, including a substantial decrease in SOD1 glycosylation mirroring those observed in the Parkinson disease SNc." (PMID 40042537, 2025). "One such therapy, Tofersen, demonstrably decreases SOD1 protein synthesis and thus may represent a viable treatment option for Parkinson disease where enhanced wild-type SOD1 synthesis appears to contribute to the formation of disSOD1 pathology." (PMID 40042537, 2025). "By contrast, significant increases (1.9-to-6.8-fold) in eight atypical SOD1 PTMs were identified in the SNc of Parkinson disease patients compared with controls, all of which have been shown to induce structural disorder and aggregation of the protein in vitro." (PMID 40042537, 2025). "We therefore proposed brain copper supplementation may improve SOD1 copper binding and mitigate the development of disSOD1 pathology in Parkinson disease." (PMID 40563111, 2025). "This indicates decreased copper binding to SOD1 specifically within the Parkinson disease SNc, which we speculate results from the combination of lower bioavailable copper and higher SOD1 protein expression we reported within this region." (PMID 40042537, 2025). "We have previously demonstrated an accumulation of immature disSOD1 conformers in the post-mortem SNc of idiopathic Parkinson disease patients, which we posit reflects decreased SOD1 copper binding consistent with our observation of a 65% decrease in copper within this brain region." (PMID 40042537, 2025). "Here we show that treatment of SOCK mice with the blood-brain-barrier-permeable copper delivery drug, diacetyl-bis(4-methylthiosemicarbazonato)copper(II) (CuATSM), mitigates the formation of Parkinson-like wild-type SOD1 pathology, increases SN dopamine neuron survival and improves motor function." (PMID 40563111, 2025). "Further, while transgenic SOD1 mice expressing mutant forms of the protein have been developed, they cannot be applied to study SOD1 pathology in Parkinson disease, which occurs in the absence of SOD1 gene mutations." (PMID 40042537, 2025). "We also engineered two of these factors - brain copper deficiency and upregulated SOD1 protein levels - into a novel mouse strain, termed the SOCK mouse, to verify their involvement in the development of Parkinson-like wild-type SOD1 pathology and their impact on dopamine neuron health." (PMID 40042537, 2025). "Alternatively, these data may justify the evaluation of therapies that decrease SOD1 protein production as effective treatments against wild-type disSOD1 pathology in Parkinson disease, such as the FDA-approved antisense oligonucleotide Tofersen." (PMID 40563111, 2025).
Parkinson disease (continued). "Soluble SOD1 protein in the degenerating Parkinson disease SNc exhibited altered post-translational modifications, which may underlie changes to the enzymatic activity and aggregation of the protein in this region." (PMID 40042537, 2025). "Our data contribute to the mounting evidence that prion-like transmission of misfolded proteins represents a common process in the pathogenesis of several neurodegenerative diseases, including α-synuclein in Parkinson's disease, Aβ and Tau in AD, and SOD1 or TDP-43 in ALS." (PMID 38862967, 2024). "While this suggests that a mutation in SOD1 is unlikely to be causally linked to Parkinson’s disease it does not exclude other possible disease-linked mechanisms associated with this protein." (PMID 35760970, 2022). "However, if feasible, such measurements would again be able to inform on the relationship between modulation of SOD1 biochemistry and therapeutic efficacy in Parkinson's disease patients." (PMID 32144830, 2021). "The degeneration of these neurons in Parkinson's disease has recently been associated with SOD1 misfolding and dysfunction,[13, 166b] and diminished SOD1 antioxidant activity augments MPTP‐induced SNc dopamine neuron loss in animal models of Parkinson's disease." (PMID 32144830, 2021). "Notably, protection against protein nitration was demonstrated, indicating a protective mechanism in the Parkinson’s disease models which was also indicated in the first study to show efficacy of CuII(atsm) in a mutant SOD1 mouse model of ALS." (PMID 33158182, 2020). "In mutant SOD1 mouse models of ALS, activation of the PERK branch appears to mediate a pro-survival response, similarly in a A53T alpha-synuclein mutation model of Parkinson’s disease." (PMID 27190028, 2016). "Based on our previous results which demonstrated that regulatory T cells were neuroprotective in a mouse model of Parkinson's disease, we evaluated whether activated T cell subsets also provide analogous protection in SOD1 Tg mice." (PMID 18648532, 2008). "A key finding in both familial and sporadic ALS is the accumulation of misfolded SOD1 proteins, which appear capable of spreading between cells in a prion-like manner, confirming data observed in other neurodegenerative diseases, e.g., Parkinson’s disease (PD)." (PMID 40710301, 2025). "This study provides the first in vivo evidence that mismetallation and altered post-translational modifications precipitates wild-type SOD1 misfolding, dysfunction, and deposition in the Parkinson disease brain, which may contribute to SNc dopamine neuron degeneration." (PMID 40042537, 2025). "We present novel insights into the pathophysiology of Superoxide Dismutase 1 (SOD1)- and in particular Fused In Sarcoma (FUS)-ALS by revealing a supposedly central role of glycolic acid (GA) and D-lactic acid (DL)—both putative products of the Parkinson’s disease associated glyoxylase DJ-1." (PMID 38760174, 2024). "Therefore, it is not surprising to confirm that SUMOylation is implicated in several human disorders such as neurodegenerative diseases associated to huntingtin, ataxin-1, tau, alpha-synuclein, DJ-1 or PARK-7 (Parkinson's disease 7), and superoxide dismutase 1 (SOD-1)." (PMID 22811915, 2012). "In the absence of SOD1 mutations, structural disorder in SOD1 protein results from altered post-translational modifications (PTMs), including decreased metal binding or atypical oxidation of key amino acid residues, although none of these factors have been examined in Parkinson disease to date." (PMID 40042537, 2025). "Our group has established that the normally protective metalloprotein superoxide dismutase 1 (SOD1) is structurally abnormal and dysfunctional specifically within vulnerable brain regions in Parkinson disease, including the SN." (PMID 40563111, 2025).
Parkinson disease (continued). "Gene silencing approaches against each amyloidogenic protein used in the treatment of neurodegenerative diseases have been developed for superoxide dismutase 1 (SOD1)-related ALS, Huntington’s disease, tauopathies, and Parkinson’s disease." (PMID 38197897, 2024). "Post-translational modifications of PDI such as S-nitrosylation (SNO-PDI) also accentuate the misfolding of synphilin in Parkinson's disease, and SNO-PDI increases mutant SOD1 misfolding via incorrect disulfide cross-linking, leading to neuronal apoptosis." (PMID 32446203, 2020). "Further data is needed to determine if anthocyanins are also able to disrupt toxic aggregate formation of other protein species, such as SOD1 in ALS and α-synuclein in Parkinson’s disease." (PMID 31443476, 2019). "This sequence of events is similar to those observed in mutant SOD1 and TDP-43 mediated NMJ degeneration and indeed central synaptic degeneration observed in transgenic models of Alzheimer’s and Parkinson’s." (PMID 29194538, 2018). "(Aβ= amyloid beta; APP= amyloid precursor protein; DJ1= Parkinson’s disease (autosomal recessive, early onset) 1; PINK1= phosphatase and tensin induced putative kinase 1; SOD1= superoxide dismutase 1)." (PMID 20938400, 2010). "Indeed, increased SOD1 protein production constitutes a key factor driving the development of disSOD1 pathology in SOCK mice and Parkinson disease." (PMID 40563111, 2025). "Neuroprotective and therapeutic outcomes from four different models of Parkinson’s disease confirm that the therapeutic implications of CuII(atsm) are not restricted to the domain of mutant SOD1." (PMID 33158182, 2020). "For example, altered hind limb movement, accompanied by some changes in coordination and stability characterized the gait abnormalities in SOD1 G93A transgenic mice, which is a model of ALS, whereas Stride Length and Stride Frequencies were found to be altered in a model of Parkinson’s disease." (PMID 31739589, 2019). "Given neither abnormal SOD1 nor dopamine neuron death, can be quantified in the living human brain, we developed the first mouse model expressing Parkinson-like wild-type SOD1 pathology to better understand the relationship between this pathology and dopamine neuron vulnerability." (PMID 40563111, 2025). "Additionally, SOD1 misfolding and aggregation under an oxidized environment are not only evident in familial and sporadic ALS but also in sporadic Parkinson’s and Alzheimer’s disease, suggesting that this pathological feature is shared among neurodegenerative diseases." (PMID 36555492, 2022). "Similar to current clinical trials of CuII(atsm) in ALS, there are no outcome measures quantifying SOD1 metalation, protein levels or catalytic activity in the current trial of CuII(atsm) in Parkinson's disease due to the likely restriction of SOD1 mismetalation to central nervous system tissue." (PMID 32144830, 2021). "In addition, similar to Parkinson’s disease, several therapeutic studies yielded positive outcomes of non-radioactive Cu-ATSM in SOD1-mutant mouse models of ALS, including improved locomotive function and overall survival." (PMID 32937849, 2020).